CLDN1 (claudin 1)
Diseases named in the same sentence as CLDN1 in open-access papers (continued):
Sharing a sentence is not in itself a finding about the gene and the disease.
colitis (continued). "In addition, ALL could ameliorate the barrier damage in colitis, as indicated by changes in the ALL group in the levels of occludin and claudin-1 converging to the control group." (PMID 36831001, 2023). "Claudin 1 expression has been reported to rise or not to change in colitis." (PMID 33803793, 2021). "In addition, XSQ treatment restored the dysregulated gut microbiota in colitis mice, increased short chain fatty acids (SCFAs) and normalized the MAPK/ERK/JNK signaling pathways, promoted expression of tight junction protein Occludin, Claudin-1, and E-cadherin proteins." (PMID 39616288, 2024). "Unlike ZO-1 and occludin, the expression of claudin 1 and claudin 2 was significantly upregulated in the majority of DSS-induced colitis mice when compared to the CTRL group without DSS treatment." (PMID 34395495, 2021).
breast carcinoma (100 papers, 2005 to 2025). "Reduced CLDN1 expression has been positively associated with poor prognoses in colon cancer, as well as tumour recurrence in lung adenocarcinoma and breast cancer." (PMID 39457456, 2024). "In breast cancers, CLDN1’s expression was significantly associated with the basal-like subtype of breast cancers." (PMID 35013251, 2022). "The basal-like subtype of breast cancer, which is typically associated with a poor prognosis, is one subtype where CLDN1 expression is elevated." (PMID 36620607, 2022). "Recent studies have suggested that Claudin-1 plays a major role in metastasis and invasion, and can be regarded as a diagnostic marker for mammary cancer." (PMID 34712723, 2021). "Studies have shown a correlation between increased malignancy, invasiveness and recurrence of breast cancer with total or partial loss of CLDN-1 expression." (PMID 31952355, 2020). "As age and differentiation have been proved to be prognostic factors for breast cancer, our results indicate the potential role of polymorphisms in CLDN1 as biomarkers for tumor invasion or prognosis." (PMID 30910845, 2019). "Recently, mutations of claudin-1 have been reported in breast cancer, which has led to claudin-1 transcript variants shorter than classical claudin-1 transcript." (PMID 31861759, 2019). "Examination of mesenchymal markers revealed that IFN-β not only inhibited the OSM-mediated expression of CD44, but also prevented repression of Claudin-1 and E-cadherin (epithelial markers associated with less aggressive breast cancers)." (PMID 31036052, 2019). "Loss of Claudin-1, a member of the tight junction, is associated with cancer invasion and the acquisition of the metastatic phenotype in breast cancer." (PMID 30112110, 2018). "Increased expression of claudin-1 has been associated with a more aggressive phenotype in breast cancer, and is associated with poor survival in ovarian cancer." (PMID 28038455, 2017). "Further, in breast cancer, a down regulation of CLDN1 has more frequently been associated with invasiveness and poor patient prognosis." (PMID 27649506, 2016). "CLDN1 transcript variant, V1, was amplified in breast cancer tissue (2/6 tumors) as well as normal human breast tissue samples (3/6)." (PMID 27649506, 2016). "Increased expression of claudin-1 and -4 is associated with basal-like breast cancer subtype, which is often related to poorer outcomes." (PMID 26083392, 2015). "A search for mutations in the promoter or coding region of the claudin 1 gene has been futile as an explanation for the down regulation of claudin 1 in breast cancer." (PMID 26633531, 2015). "Further, in vitro studies showed that re-expression of claudin 1 alone was sufficient to induce apoptosis in a human breast cancer cell line, MDA-MB361, and a loss of expression led to neoplastic transformation of mammary epithelial cells." (PMID 26633531, 2015). "Low expression of CLDN1 was associated with epigenetic regulation in estrogen positive breast cancer." (PMID 26067567, 2015). "In oral squamous cell carcinoma and in breast cancer, the loss of claudin 1 has been associated with higher recurrence status and shorter disease free survival." (PMID 26633531, 2015). "Our analysis shows that DNA promoter methylation is associated with downregulation of claudin 1 in a subgroup of breast cancers that include mostly ER+ tumors." (PMID 23844228, 2013). "Down-regulation of claudins has also been reported in some other epithelial tumors, including loss of claudin-1 in breast cancer and colonic cancer, as well as the loss of claudin-7 in breast cancer and head and neck cancer." (PMID 24073219, 2013). "We found that methylation of the claudin 1 promoter CpG island is relatively frequent in estrogen receptor positive (ER+) breast cancer and is associated with low claudin 1 expression." (PMID 23844228, 2013).
breast carcinoma (continued). "Downregulation of the tight junction protein claudin 1 is a frequent event in breast cancer and is associated with recurrence, metastasis, and reduced survival, suggesting a tumor suppressor role for this protein." (PMID 23844228, 2013). "As we have previously shown, there is a positive association between claudin 1 expression and ER-ve breast cancers." (PMID 23721519, 2013). "Claudin-1 expression is upregulated in association with older age in women with basal-like breast cancer, suggesting the potential value of claudin-1 for the identification of specific groups of patients with basal-like breast cancer." (PMID 24009024, 2013). "Indeed, CLDN1 downregulation was associated with a more malignant phenotype in non-invasive T-47D breast cancer cells." (PMID 36291810, 2022). "In addition, CLDN1 was also found to be associated with the malignancy of hepatocellular carcinoma, cervical cancer, breast cancer, and gastric cancer." (PMID 36193204, 2022). "CLDN1 has been studied in cancer progression and an association between CLDN1 expression and poor prognosis or survival was reported in colon and breast cancers." (PMID 33828978, 2021). "Loss of expression of tight junction proteins such as Claudin-1 might be assumed to lead to cellular metastasis and detachment, as commonly seen in breast carcinoma." (PMID 34712723, 2021). "CLDN1-deficient breast cancer cell subpopulation reflects a CSC phenotype 42." (PMID 32754286, 2020). "Due to the disruption of intracellular adhesion and enhanced motility, the loss of claudin-1 is associated with tumor cell invasiveness, high recurrence status, and a shorter recurrence-free survival in breast cancer, oral squamous cell carcinoma, and gastric carcinoma patients." (PMID 31717460, 2019). "However, several migratory and invasive cancerous cell types have been associated with high expression of claudin-1 including breast cancer, colon cancer, liver cancer, oral squamous carcinoma, and melanoma." (PMID 31404237, 2019). "Down-regulation of CLDN1 was associated with shorter DFS of breast cancer patients." (PMID 30910845, 2019). "Interestingly, with regard to CLDN1 SNPs in breast cancer, to date, only one mutation, p.V85G, has been identified in one of 993 patient samples analyzed in the Cancer Genome Atlas project." (PMID 27649506, 2016). "We have identified a number of CLDN1 transcript variants, and propose that other epigenetic factors such as transcript variant utilization may be another mechanism by which CLDN1 is regulated in breast cancer." (PMID 27649506, 2016). "Here, in the present study, we now show that in breast cancer there are numerous CLDN1 transcript variants suggesting that alternate splicing may be another mechanism of CLDN1 deregulation." (PMID 27649506, 2016). "Loss of CLDN1 has been reported to stimulate the tumor progression and invasion in some cancers, including prostate cancer, breast cancer and melanocytic neoplasia, while in esophageal squamous cell carcinoma, increased expression of CLDN1 was correlated with tumor progression." (PMID 27974683, 2016). "Next we wanted to examine whether there was a relationship between claudin 1 protein level in the breast cancer specimens and the presence of transcript variants or SNPs." (PMID 27649506, 2016). "In this study, we report for the first time, numerous CLDN1 transcript variants in breast cancer." (PMID 27649506, 2016). "Furthermore, a causal role for claudin 1 in breast cancer progression has recently been demonstrated in some breast cancer cell lines." (PMID 26633531, 2015). "A dysregulation of claudin 1 in cancer has been well documented, and both a loss and gain has been associated with several cancers including oral, lung, prostate and gastric carcinoma as well as breast cancer." (PMID 26633531, 2015).
breast carcinoma (continued). "Furthermore, we identified a significantly high association with claudin 1 and the basal-like subtype of breast cancers, an aggressive form of breast cancer, which to date remains poorly characterized." (PMID 26633531, 2015). "There have been many speculations about the mechanisms responsible for claudin 1 loss in ER+ breast cancers." (PMID 26633531, 2015). "Moreover, loss of claudin 1 correlates with breast cancer recurrence, metastasis, and reduced survival." (PMID 23844228, 2013). "However, our results concordantly indicate that DNA promoter methylation is causally associated with downregulation of claudin 1 in a group of breast cancers that include mostly ER+ tumors." (PMID 23844228, 2013). "The significant loss of CLDN1 protein in breast cancer cells suggests that CLDN1 may play a role in invasion and metastasis." (PMID 15743508, 2005). "This could be a cause for the cytoplasmic accumulation of CLDN-1 in some breast cancer cell lines." (PMID 31952355, 2020). "Therefore, further investigation is required to determine whether CLDN1 expression is correlated with the development of different subtypes of breast cancer, and understand the molecular mechanisms underlying the role of CLDN1 in metastasis." (PMID 26067567, 2015). "In a study conducted in breast carcinomas by Kramer and coworkers in 2000 it was shown that there are no genetic alterations in the promoter or coding sequences in the CLDN1 gene that could account for the loss of CLDN1 protein expression in tumour cells." (PMID 15743508, 2005). "In breast cancer, the expression frequency of CLDN1 is low, but in addition to EphB4, LAT1 is expressed at high frequencies." (PMID 40076777, 2025). "This is somewhat analogous to CLDN1’s protective role in lung and breast cancers, suggesting that in certain epithelial tumors CLDN1 helps preserve junctional integrity and epithelial phenotypes." (PMID 40687428, 2025). "Sp1, the first identified transcription factor in the specific protein/Kruppel-like factor family, has been reported to promote Cldn1 expression in the intestinal epithelium and human breast cancer epithelium." (PMID 40940777, 2025). "Due to its broad regulatory function, CLDN1 is influenced by various pathways, including regulation by ADAM15 through the PI3K/Akt/mTOR pathway, which is associated with breast cancer signaling." (PMID 40507913, 2025). "Existing studies have demonstrated that Stanniocalcin-2 (STC2) can regulate the protein kinase C/CLDN1 pathway to inhibit breast cancer invasion and metastasis." (PMID 40687428, 2025). "Conversely, overexpression of CLDN1 in triple negative “claudin 1 low” in the basal-like breast cancer cell line MDA-MB-231 inhibits cell migration and results in elevated cell adhesion with β-catenin localization to adherence junctions." (PMID 38942893, 2024). "Hereby, our findings advocated the expression of IHC, namely, cyclin D1 and claudin-1, in cases of breast cancer." (PMID 40034931, 2024). "In a quest for a better, cost-effective approach, researchers proposed the selection of surrogate IHC markers such as cyclin D1 and claudin-1 for the prognosis of breast cancer patients, supplementing the traditional ER, PR, and HER2/neu receptor." (PMID 40034931, 2024). "Our findings advocated the expression of IHC namely, cyclin D1 and claudin-1, in cases of breast cancer." (PMID 40034931, 2024). "The role of CLDN1 as a tumor suppressor has been demonstrated in prostate cancer, lung adenocarcinoma, and estrogen receptor–positive subtypes of breast cancers." (PMID 37318881, 2023). "In breast cancer, the expression of claudin-1 was found to be downregulated in estrogen receptor (ER)-positive luminal A and luminal B breast cancer, while increased expression was observed in ER-negative basal-like breast cancer subtype." (PMID 36614243, 2023).
breast carcinoma (continued). "CLDN1 role in apoptosis in other cancer types remains controversial because both anti-apoptotic and pro-apoptotic roles were described in breast cancer cell lines." (PMID 37041570, 2023). "KT significantly increases claudin expression, facilitating lower recurrence status and more prolonged disease-free survival in breast cancer; however, overexpression of claudin 1 increases cell invasion in colon cancer." (PMID 36674719, 2023). "In the rest of cancers of the breast, claudin-1 was found to play the role of a tumour enhancer/facilitator." (PMID 37102018, 2023). "Epigenetic silencing by DNA hypermethylation of other CLDNs have also been described, such as CLDN1 in podocytes and breast cancer and CLDN4 in bladder cancer." (PMID 36614243, 2023). "And finally, we have presented possible use of claudin-1 in predicting pCR, a recent important prognostic indicator of breast cancer." (PMID 37102018, 2023). "In most breast cancers, downregulation of CLDN1 is more frequently correlated with higher invasiveness and poor prognosis." (PMID 36620607, 2022). "For example, the claudin-1 expression level in breast cancer differs depending on the subtype of cancer." (PMID 34808689, 2022). "Taken together, the results established the important role of CLDN1 in TNBC breast cancer cells chemosensitivity and contribute to better understand its mechanism of action." (PMID 36291810, 2022). "Expression of claudin-1 is significantly higher in the poor prognosis breast cancer than in other subtypes." (PMID 34808689, 2022). "CLDN1 promotes the growth and progression of various tumors, including breast cancer, melanoma, oral squamous cell carcinoma, thyroid cancer, ovarian cancer, colon cancer, gastric cancer, hepatocellular carcinoma, and pancreatic cancer." (PMID 36620607, 2022). "Although CLDN1 role in breast cancer is still ill-defined, several in vitro studies agree to the notion that CLDN1 is a tumor suppressor." (PMID 36291810, 2022). "We demonstrated that CLDN1 increased the sensitivity of TNBC cell lines to the main chemotherapeutic agents commonly used for breast cancer treatment." (PMID 36291810, 2022). "In breast cancer, claudin-1 acts as a tumor suppressor in ER-positive cancer and as a tumor promoter in ER-negative cancer." (PMID 34354941, 2021). "A similar change in claudin localization has been reported for CLDN1 in breast cancer, colon cancer and tongue carcinoma; the localization of CLDN1 changes from the membrane to the cytoplasm as the malignancy progresses." (PMID 34131154, 2021). "Evidence has also been found that claudin-1 regulates apoptosis in human breast cancer cells through deactivation of pro-caspase-8." (PMID 33784242, 2021). "The knockdown of claudin-1 in a basal-like subtype human breast cancer cell line resulted in reduced cancer cell migration." (PMID 32309226, 2020). "CLDN-1 also possesses tumor-promoting effects by increasing cell migration and by exhibiting anti-apoptotic effects in some breast cancer cell lines like MCF-7." (PMID 31952355, 2020). "Claudin-1, the first claudin family member identified, is downregulated in hepatocellular carcinoma, breast cancer and lung adenocarcinomas." (PMID 32309226, 2020). "CLDN-1 expression has also been observed in a small percentage of invasive human breast cancers that exhibit different pathological lesions leading to complexity in CLDN-1 expression." (PMID 31952355, 2020). "Several proteins interact with CLDN-1 to fuel the progression of breast cancer, including the following: Ephrin B1, ESCRT, CD9 and EpCAM." (PMID 31952355, 2020). "Studies have shown the direct involvement of CLDN-1 in the development and progression of several cancers, such as colon cancers, oral squamous cell carcinomas, breast cancers, melanomas, and in many other cancers as discussed in this review." (PMID 31952355, 2020).